BDNF (brain derived neurotrophic factor)
Diseases named in the same sentence as BDNF in open-access papers (continued):
Sharing a sentence is not in itself a finding about the gene and the disease.
cognitive decline (continued). "It is believed that the higher enhancements of BDNF disposal related to larger volumes of AE are capable of counteract both cognitive decline and the risk of dementia." (PMID 28469588, 2017). "In this data set, we independently confirmed the strong association of REST with other candidate plasma proteins of cognitive decline at baseline: BDNF (r=0.5, P<0.001), RANTES (r=0.421, P=0.002) and PAI-1 (r=0.321, P=0.026)." (PMID 28585932, 2017). "Recently, in a large longitudinal study on cognitively healthy individuals at risk for AD, the BDNF Val66Met was demonstrated to predict cognitive decline due to AD." (PMID 29249935, 2017). "Carriage of 1 or 2 Met alleles is associated with lower BDNF production, decreased hippocampal volume, and cognitive decline." (PMID 35098038, 2017). "Buchman and colleagues reported the association between slower rates of cognitive decline with higher levels of BDNF expression in AD individuals." (PMID 35098038, 2017). "Many potential mechanisms have been proposed to underlie diet-induced cognitive decline and we will focus on inflammation and the neurotrophic factor, brain-derived neurotrophic factor (BDNF)." (PMID 26274972, 2015). "Laske C and colleagues have shown that higher BDNF serum levels are associated with a slower rate of cognitive decline in AD patients." (PMID 26114940, 2015). "BDNF participates in regenerative processes, and decreased BDNF function is associated with neurodegeneration, cognitive decline, and psychiatric disorders." (PMID 23785422, 2013). "In regards to a relationship of BDNF with cognitive decline, there was a significant association with rs11030094 and change in ADAS-Cog score in the ND group, and rs11030108 in the MCI group." (PMID 24086677, 2013). "Three out of eight BDNF SNPs analyzed were significantly associated with measures of cognitive decline (rs1157659, rs11030094, rs11030108)." (PMID 24086677, 2013). "We also identified a highly conserved sequence 21 kilobase 5' of BP4 that we called BE5.2, which contains rs12273363, a polymorphism associated with decreased BDNF expression, mood disorders, and cognitive decline." (PMID 22265241, 2012). "In contrast, we found significant correlations between serum BDNF, proBDNF levels and MoCA scores, suggesting that these neurotrophic signaling deficits may be linked to the cognitive decline observed in acromegaly patients." (PMID 41550023, 2026). "While further studies are required to elucidate the precise role of the adipose CX3CL1-mediated regulation of BDNF expression, studies on white adipose tissue may provide new therapeutic targets for preventing age-associated cognitive decline." (PMID 40724847, 2025). "Lower BDNF levels in the blood and brains of AD patients are associated with cognitive decline." (PMID 40027104, 2025). "By examining how BDNF genetic and epigenetic regulation shape BDNF expression and consequently cognitive abilities, we aim to elucidate pathogenic mechanisms underlying cognitive decline and assess the translational potential of peripheral BDNF-based biomarkers for dementia." (PMID 41009553, 2025). "Cognitive decline in type 2 diabetes and heavy metal exposure is closely linked to disruptions in cholinergic neurotransmission and neurotrophic support, particularly through alterations in AChE activity and BDNF levels." (PMID 40726602, 2025). "The authors considered the implications of BDNF in these deficits and found that the cognitive decline is linked to the lowered levels of BDNF, the damage to synaptic plasticity, and the diminished excitability of the glutamatergic neurons in the CA1 area of the hippocampus." (PMID 41465304, 2025). "Whether it be neurodevelopmental health promotion in children or treatment for age-associated cognitive decline, the possibilities of BDNF are limitless." (PMID 40362507, 2025).
cognitive decline (continued). "Similarly, BDNF has been shown to have a critical role in synaptic function and neuroplasticity, and its reduced levels are associated with cognitive decline in AD." (PMID 40656325, 2025). "Thus, in vivo and in vitro studies have shown that butyrate can counteract cognitive decline and loss of neuronal spines and prevent low BDNF levels by maintaining gut integrity." (PMID 40871332, 2025). "For example, in neurodegenerative conditions such as Parkinson’s and Alzheimer’s disorders, significantly decreased BDNF has been disclosed, which may contribute to the advancement of cognitive decline and neuronal loss." (PMID 39596862, 2024). "One Study has shown that cognitive decline is more rapid in patients with coronary artery disease than in healthy individuals, which is associated with lower circulating levels of brain-derived neurotrophic factor (BDNF) and insulin-like growth factor I, among others." (PMID 38707889, 2024). "Hence, future investigations need to prioritize elucidating the complex mechanisms underlying BDNF function in the aging brain, particularly its role in enhancing resilience to aging-related cognitive decline and neurodegenerative disorders." (PMID 39656488, 2024). "Because, insulin resistance, a common concern in aging, (e.g., brain-specific insulin signaling deficiencies in the early stages of AD pathogenesis,) is linked to cognitive decline, BDNF interaction with insulin is crucial for maintaining energy metabolism and cognitive function." (PMID 39656488, 2024). "Decreases in BDNF are associated with aging and may contribute to neurodegeneration and cognitive decline while increases may represent a transient compensatory response." (PMID 38534322, 2024). "Overall, the available evidence suggests that HF may promote cognitive decline by stimulating neuroinflammation, by causing an increase in Ang II levels, and by down-regulating BDNF expression." (PMID 39457698, 2024). "One study showed that high levels of peripheral inflammatory-cytokines, oxidative stress and reduced levels of BDNF were associated with poor cognitive performance, demonstrating a link between cognitive decline observed in BD and neuroinflammatory and neuroprotective mechanisms." (PMID 38773397, 2024). "Hence, this research aims to explore how SIRT1/BDNF impacts cognitive decline caused by anesthesia/surgery in aged mice." (PMID 38783169, 2024). "Therefore, when elderly females begin to age, they must exercise regularly and continuously to avoid an increase in Aβ and a decrease in BDNF, risk factors of AD, thereby preventing cognitive decline and maintaining and improving their quality of life." (PMID 38337492, 2024). "In addition to the reduced BDNF in the patients’ brains, the clinical relevance of altered serum BDNF levels in AD becomes apparent when examining their associations with cognitive decline." (PMID 38338875, 2024). "As already mentioned, aging is associated with cognitive decline and reductions in available BDNF." (PMID 39194496, 2024). "Given the established role of BDNF, particularly its Val66Met polymorphism, in the pathogenesis of cognitive decline associated with neurodegeneration, it is plausible to suspect an association between BDNF and vascular cognitive impairment linked to atherosclerosis as well." (PMID 39619329, 2024). "Allelic variation in the brain-derived neurotrophic factor (BDNF) Val66Met polymorphism has been shown to moderate rates of cognitive decline in preclinical sporadic Alzheimer’s disease (AD; i.e., Aβ + older adults), and pre-symptomatic autosomal dominant Alzheimer’s disease (ADAD)." (PMID 38454193, 2024). "In addition, the Val/Met single nucleotide polymorphism at codon 66 of the brain-derived neurotrophic factor (BDNF) gene has been associated with a higher risk for meth abuse, while it has also been linked to cognitive decline in PD." (PMID 37691228, 2024).
cognitive decline (continued). "Loss of BDNF may also accelerate aging, which is postulated to be a mechanism that leads to cognitive decline in patients receiving chemotherapy." (PMID 36720792, 2023). "Enhancing BDNF expression could thus be a strategy to prevent the loss of neurons and hence to slow down the cognitive decline in neurodegenerative conditions." (PMID 39081970, 2023). "There was an association between vitamin D on serum BDNF and on cognitive decline in older adults." (PMID 36629701, 2023). "It has been reported that a decrease in cerebrospinal fluid BDNF levels may be associated with cognitive decline in healthy individuals." (PMID 36979505, 2023). "BDNF can potentially be used as an objectively accurate AD biomarker as it correlates and is directly linked with the cerebral phenomenon of AD, and decreased BDNF levels are also correlated with the degree of cognitive decline and neurological impairment reflecting the AD progressivity." (PMID 38053647, 2023). "In addition, we found that HFD feeding led to a greater reduction in BDNF levels and elevation in AChE activity in the hippocampus of male rats compared to females, suggesting that obese males are at a greater risk for cognitive decline." (PMID 36977735, 2023). "A causative BDNF rs6265 polymorphism is associated with cognitive decline and increased AD risk." (PMID 37008787, 2023). "These areas are supplied with fresh blood that is rich in oxygen and, in addition, with increased BDNF as an underlying factor in exercise/training-induced positive effects on CNS, which may result in an inhibition of cognitive decline due to hypoxia." (PMID 36834322, 2023). "Although, it remains unclear whether BDNF changes in PD and AD are a cause or consequence of disease, the first phase-I clinical trial of BDNF gene therapy for cognitive decline in AD commenced last year." (PMID 36621964, 2023). "In addition, we showed that miR-206 targets BDNF to improve cognitive decline by exploring key intermediate molecules associated with the signaling pathway, suggesting further studies on the regulation mechanism of its internal signal pathway." (PMID 35781287, 2022). "The reduced binding of BDNF-Val66Met to Sortilin may explain the faster cognitive decline in AD that harbors this mutation." (PMID 36397124, 2022). "A dearth of CREB or BDNF is associated with cognitive decline." (PMID 35615594, 2022). "Intralateral ventricle injection of adeno-associated virus carrying the human BDNF gene restored neuronal degeneration, synaptic loss, and cognitive decline in the Morris water maze, Y-maze, and novel objects recognition tests but did not reverse the tau hyperphosphorylation level." (PMID 35887075, 2022). "IGF-1 and brain-derived neurotrophic factor (BDNF) deficiency have been linked to cognitive decline and dementia in older adults, whereas older adults who underwent a 24-week physical activity intervention experienced an increase in IGF-1 concomitant with improvements in cognitive function." (PMID 35436329, 2022). "In addition, high intellectual enrichment predicted slower cognitive decline and counteracted the detrimental effect of the Met66 allele in brain-derived neurotrophic factor." (PMID 36519153, 2022). "Presence of one or two BDNF rs56164415 T alleles was related to cognitive decline in PTSD." (PMID 33926045, 2021). "Reflecting the growing interest in the assessment of BDNF as a clinically useful biomarker for the prevention of cognitive decline, there has been an increasing number of observational studies reporting data on the association of circulating BDNF levels with cognitive functioning." (PMID 34239422, 2021). "As BDNF plays a role in memory formation, enhanced levels of BDNF in the brain may help prevent memory loss and cognitive decline with ageing." (PMID 34127029, 2021). "Indeed, BDNF polymorphisms were reported to moderate Aβ-related cognitive decline in preclinical AD, and BDNF reduces Aβ in the brain." (PMID 34226487, 2021).
cognitive decline (continued). "However, BDNF rs56164415 was significantly associated with cognitive decline in all tested models in veterans with PTSD (both smokers and non-smokers) and in control subjects who were non-smokers." (PMID 33926045, 2021). "BDNF deficiency is closely associated with cognitive decline." (PMID 32460803, 2020). "Furthermore, a study in healthy older adults showed an association of lower CSF BDNF levels with poorer memory performance and faster cognitive decline." (PMID 30403004, 2019). "Since BDNF decreases throughout life, it would be interesting to assess the possible associations between the Val/Met polymorphism and age-related cognitive decline." (PMID 31440144, 2019). "Since RAGE and BDNF expressions were significantly changed in the animal model, it is very likely that sevoflurane inhalation caused cognitive decline in the processes of learning and memory through triggering neuroinflammation and neurotoxicity in the hippocampus tissue." (PMID 30402039, 2018). "Several heritability studies have reported that the Brain Derived Neurotrophic Factor (BDNF) Val66Met genetic polymorphism could contribute to the acceleration of cognitive decline in aging." (PMID 30333719, 2018). "This suggests that high Aβ level might have been a necessary condition for cognitive decline in this context and that BDNF Val66Met polymorphism has a downstream moderation of the effect of Aβ in executive function." (PMID 29858545, 2018). "In addition, low levels of BDNF correlate with the degree of cognitive decline and low levels of cystatin C are associated with an anticipation of dementia onset." (PMID 29249935, 2017). "Taking into account the fact that BDNF is closely linked with cognition, it is of great interest to explore the neuroprotective agents that may attenuate the cognitive decline due to diabetes." (PMID 24857910, 2014). "We sought to determine the correlates of BDNF level and whether BDNF level was prospectively associated with cognitive decline in healthy older adults." (PMID 24670553, 2014). "We evaluated the association between BDNF and cognitive decline with longitudinal models." (PMID 24670553, 2014). "Second, we aimed to evaluate the association between BDNF and cognitive decline, especially after consideration of potential confounders using a large prospective cohort of cognitively healthy older adults with cognitive performance evaluated at multiple time points over a lengthy follow-up." (PMID 24670553, 2014). "Of great interest is that the onset of cognitive decline was closely associated with the accumulation of soluble Aβ, disruption of synaptic activity, alteration in the BDNF system, and a defective production in the subset of CX3CR1lowLy6-ChighCCR2+Gr1+ monocytes." (PMID 23125823, 2012). "Limited existing literature suggests that low BDNF levels in the cerebrospinal fluid (CSF) are associated with cognitive decline, both cross-sectionally and longitudinal; however, little is known about the association of peripheral BDNF levels with either brain structure or cognition in late life." (PMID 22523577, 2012). "Reduced CSF BDNF was associated with age-related cognitive decline, suggesting a potential mechanism that may contribute in part to cognitive decline in older individuals." (PMID 19412541, 2009). "Furthermore, in AD patients, dysregulation of BDNF signaling is associated with cognitive decline." (PMID 40380033, 2025). "With respect to BDNF, while our results in animals, as well as some clinical studies, show reduced levels after chemotherapy and its association with cognitive decline, other reports indicate increased levels in cancer patients, where BDNF may promote tumor growth, maturation, and invasion." (PMID 41155372, 2025).
cognitive decline (continued). "Therefore, the present study aims to investigate the effect of circuit training on β-amyloid, BDNF, and cognitive function in untrained obese elderly Korean women aged 65 to 70, who are at a higher risk of developing dementia and accelerated cognitive decline than elderly males." (PMID 38337492, 2024). "In addition, cognitive decline may also be associated with systemic brain-derived neurotrophic factor (BDNF) levels." (PMID 38114553, 2023). "Therefore, this study aims to estimate the association between vitamin D and cognitive decline of older adults and evaluate whether this association is mediated by BDNF serum concentration." (PMID 36629701, 2023). "Furthermore, decreased BDNF has been linked to cognitive decline." (PMID 37155025, 2023). "We hypothesized that cognitive function would be reduced due to stress-related structural changes in the brain, and this cognitive decline was expected to be reflected by a decrease of neurotrophic factors BDNF and IGF-1, as these factors are highly associated with cognitive function." (PMID 36798941, 2023). "Thus, modulation of BDNF and TrkB signaling are important factors in cancer and cancer-therapy and may also be important to cognitive decline associated with cancer treatment." (PMID 37788996, 2023). "Thus, decreased Bifidobacterium in DLB and PDD+ may be causally associated with cognitive decline via decreased BDNF." (PMID 36494405, 2022). "Indeed, BDNF is decreased in the pre-clinical stages of AD and serum BDNF levels are associated with cognition and may predict a slower rate of cognitive decline." (PMID 33661922, 2021). "The BDNF gene has a common single nucleotide polymorphism causing a valine to methionine amino acid substitution at residue 66 (Val66Met) and Met allele carriers have been shown to exhibit reduced synaptic activity and greater cognitive decline compared to Val/Val homozygotes." (PMID 34408648, 2021). "In summary, our findings suggest that cognitive activity may increase everyday functioning and BDNF levels, at least in a subset of vulnerable participants who began the 6-week intervention with low BDNF levels, which may help reduce the risk for cognitive decline and AD." (PMID 35822037, 2021). "Therefore, whether carriers of the Met allele are truly protected against cognitive decline remains controversial, implying that the BDNF Val66Met polymorphism may contribute to varying cognitive function." (PMID 30382534, 2019). "Because BDNF is a key mediator of synaptic efficacy in circuits critical for cognition, it has long been suspected that disruption of BDNF signaling systems might play a significant role in aging-associated cognitive decline." (PMID 29911174, 2018). "A clinical study involving 535 old participants who underwent annual cognitive assessments and brain autopsy at death showed that higher brain BDNF expression is associated with slower cognitive decline and BDNF may also reduce the deleterious effects of AD pathology on cognitive decline." (PMID 27429982, 2016). "Therefore, the present study was aimed to investigate whether the BDNF signaling pathway is directly involved in the protective effect of curcumin on cognitive decline in AD and to identify this disease’s underlying mechanisms." (PMID 26114940, 2015). "According to this view, decreased levels of BDNF could contribute to the neurite atrophy and synaptic loss observed in the brains of AD patients, and up-regulation of BDNF could control the progression of AD and cognitive decline." (PMID 25849905, 2015). "The levels of serum BDNF, which is believed to reflect the levels of BDNF in the brain, decreases in AD patients when compared to age-matched healthy controls, and higher levels of serum BDNF are reportedly associated with a slower rate of cognitive decline in AD patients." (PMID 26114940, 2015).